BDNF (brain derived neurotrophic factor)
Diseases named in the same sentence as BDNF in open-access papers (continued):
Sharing a sentence is not in itself a finding about the gene and the disease.
heart failure (continued). "In particular, elevated BDNF levels have been associated with decreased risk of coronary events and mortality, while, reduced BDNF levels have been detected in CAD and in heart failure patients, and related to endothelial function." (PMID 34205863, 2021). "BDNF levels are reduced in heart failure patients and are positively correlated with the peak of oxygen uptake (VO2)." (PMID 32443765, 2020). "Using data from a large population based study we demonstrate that low BDNF is related with higher levels of the heart failure biomarker NTproBNP and with adverse left ventricular cardiac remodeling." (PMID 31659205, 2019). "Three studies reported the efficacy of circulating BDNF levels in predicting adverse events in patients with heart failure." (PMID 30133549, 2018). "BDNF is also involved in cardiac remodeling in heart failure patients." (PMID 38707889, 2024). "Correlation analysis showed that TNFSF10 was positively correlated with the expression of homocysteine, COL1α2 and BDNF, while negatively correlated with EF, suggesting that TNFSF10 might be associated with heart failure." (PMID 38145212, 2023). "Additionally, BDNF increases the exercise capacity in heart-failure mice due to the enhancement of fatty acid oxidation via the activation of the AMPKα-PGC1α pathway." (PMID 36078878, 2022). "However, during ventricular dysfunction, both plasma and serum BDNF levels are reduced, and a low BDNF concentration was positively correlated with heart failure severity and prognosis." (PMID 36078878, 2022). "In addition, it has been reported that homozygous systemic BDNF knockout mice die due to Heart failure (HF) in the fetal period." (PMID 36061561, 2022). "Circulating BDNF levels have been previously related to cardiovascular disease, and several studies have recently suggested its prognostic relevance in patients with hypertension, diabetes mellitus, Chagas’ cardiomyopathy, heart failure, and CAD." (PMID 34205863, 2021). "Our data indicate that animals with persistent lower BDNF levels were vulnerable to cardiac hypertrophy, and may suggest that Dlow can present heart failure sensitivity." (PMID 33344701, 2020). "Furthermore, reduced serum levels of BDNF were associated with all-cause cardiac death and readmission in heart failure patients, suggesting that this myokine could be a less invasive biomarker that shows the severity of heart failure and can work as a predictor of prognosis in these patients." (PMID 32443765, 2020). "Recent clinical trials reported lower levels of BDNF in heart failure patients." (PMID 31659205, 2019). "In addition, BDNF levels are also reduced in heart failure patients and are inversely correlated with BNP8." (PMID 31659205, 2019). "However, our sample size is in agreement with a prognostic study of BDNF in patients with heart failure." (PMID 30133549, 2018). "Thus, the baseline concentration of serum BDNF and the cut-off point in predicting cardiac death were expected to be lower in patients with heart failure due to ChC than in other aetiologies." (PMID 30133549, 2018). "Low serum BDNF level was found in patients with chronic heart failure and was positively correlated with heart failure severity, indicating that BDNF may play a role in heart failure." (PMID 28770018, 2017). "Since BDNF-treatment might constitute a therapeutic option for treatment of end stage heart failure, we tested the impact of BDNF on cardiac homeostasis by a pulsed SILAC approach to quantitatively monitor proteins synthesized after treatment." (PMID 25799225, 2015). "We further provided supporting evidence on the regulatory role of exogenous BDNF on migration, proliferation and survival of progenitor cells, which might offer a therapeutic option for treatment of heart failure." (PMID 25799225, 2015).
heart failure (continued). "This study investigates whether the BDNF Val66Met (rs6265) and ATP2A2 rs1860561 polymorphisms are associated with a differential therapeutic response to low-dose empagliflozin in patients with heart failure." (PMID 41007658, 2025). "Therefore, in the future, BDNF may also be used as a circulating marker for the identification of cardiac remodeling and dysfunction in heart failure patients." (PMID 38707889, 2024). "Likewise, the overactivation of the sympathetic nervous system during heart failure may increase the circulating glucocorticoid concentration, which, in turn, reduces BDNF release from the hippocampus." (PMID 36078878, 2022). "Exogenous BDNF (i) stimulated migration, which might improve the homing ability of Sca-1 cells derived from the failing heart and (ii) repressed the cell cycle progression suggesting its potency to ameliorate heart failure." (PMID 25799225, 2015). "An observational clinical study showed that in ambulatory stable heart failure patients with LVEF <50%, those with lower serum BDNF concentrations had more severe cardiac remodeling and dysfunction and higher NT-proBNP levels." (PMID 38707889, 2024). "Also, another study showed that BDNF generation could limit chronic postischemic heart failure." (PMID 38020715, 2023). "Interestingly, while BDNF, which increases tubulin tyrosination, H3‐Ser‐ADPR and TyrRS in neurons protects against heart failure, trans‐RSV, which decreases tubulin tyrosination, H3‐Ser‐ADPR and TyrRS, increases the risk of CVDs." (PMID 40476370, 2025). "Reduced levels of brain-derived neurotrophic factor, decreased expression of BDNF and its receptor, the pro-myosin-related kinase receptor (TrkB), in cardiomyocytes, and impaired energy metabolism in cardiac cells have been found in patients with heart failure." (PMID 38707889, 2024). "Hence, our results extend the current knowledge by providing evidence for a putative role of BDNF not just in heart failure but also during subclinical cardiac dysfunction and remodeling prior to manifest cardiac disease." (PMID 31659205, 2019).
retinal degeneration (35 papers, 2010 to 2026). Degeneration of the retina. "Based on the involvement of retina in nervous system, these observed alterations in BDNF levels would associated with the process of retinal degeneration in AMD." (PMID 33604378, 2021). "As demonstrated in a human study, ALA also promotes the production of brain-derived neurotrophic factor (BDNF), a protein that safeguards neurons from damage and supports their survival, thus preventing retinal degeneration." (PMID 39857340, 2024). "The local synthesis and retrograde transport of BDNF is significantly reduced after excitotoxic stimuli, leading to retinal degeneration, and chronic high IOP induces the loss of BDNF in RGC cell bodies." (PMID 37686046, 2023). "Further research is certainly required to clarify the dose and period of BDNF prescription regarding the level of retinal degeneration in diabetic retinopathy." (PMID 32509339, 2020). "We suggest that BDNF delivery to the eye is needed to be under precise control depending on the rate of retinal degeneration." (PMID 32509339, 2020). "The results of this study also shed light on mechanisms of chronic retinal degeneration, identifying exogenous BDNF as a prospective regulatory factor for retinal tissue." (PMID 30759764, 2019). "Mice that fasted every other day were found to have increased retinal histone acetylation, which was accompanied by decreased retinal degeneration, increased visual function, and upregulation of Brain Derived Neurotrophic Factor (BDNF) and catalase." (PMID 28210622, 2017). "Pardue and colleagues found aerobic exercise to have a neuroprotective effect on photoreceptors in mouse models of retinal degeneration which they demonstrated was mediated through increases in brain-derived neurotrophic factor (BDNF)." (PMID 28596918, 2017). "Previous reports showed that intravitreal injection of BDNF at concentrations comprised between 1 and 10 μg/μl was able to protect retinal cells in different animal models of retinal degeneration." (PMID 25536045, 2014). "Brain-derived neurotrophic factor (BDNF) has been reported to prevent retinal ganglion and amacrine cell death and can also rescue photoreceptor loss in animal models of retinal degeneration." (PMID 23289056, 2011). "In addition, BDNF has been proposed as a therapeutic option for retinal degeneration and neuroprotection due to its strong neurotrophic actions." (PMID 31509934, 2019). "Perhaps more importantly, this also suggests that knockdown of miR-125b-5p, or subretinal injection of BDNF, could potentially rescue vision in retinal degeneration." (PMID 28432360, 2017). "Indeed, studies have reported that intraocular administration of NTs promotes the survival of GCs and axons after injuries and, in particular, the intraocular administration of BDNF has shown a protective action on photoreceptors in retinal degeneration and retinal detachment." (PMID 38473977, 2024). "The highest SF3/SF1 proteins are known to have antioxidant effects, including NGF, BDNF, PEDF, and LIF, suggesting that SF3 would have greater antioxidant effects and efficacy in models of retinal degeneration." (PMID 37443724, 2023). "GFs such as neural growth factor (NGF), brain-derived neurotrophic factor (BDNF) and ciliary neurotrophic factor (CNTF) can significantly slow retinal degeneration and stop the progression in clinical and preclinical trials." (PMID 31931872, 2020). "Intravitreal delivery of LIF, CNTF, brain-derived neurotrophic factor (BDNF), or FGF2 promotes survival of photoreceptors after light damage or inherited retinal degeneration, and protects retinal ganglion cells after ischemic injury." (PMID 22701694, 2012). "It has been proposed that MCs are a major cellular source of BDNF, which has been used in clinical trials for retinal neuroprotection in various non-DR-related retinal degenerations for decades and is now being considered for clinical trial for DR." (PMID 34068807, 2021).
retinal degeneration (continued). "In contrast, BDNF cannot successfully cross the blood-brain barrier, and thus, it is not surprising that there are no studies to date reporting BDNF's therapeutic effects for retinal degeneration." (PMID 33014446, 2020). "Transduction of nontarget cells may also contribute, and glial BDNF and TrkB signaling has previously been shown to play an important role in neural protection after traumatic optic nerve injury and can delay retinal degeneration." (PMID 33789891, 2021).
Atrophy (33 papers, 2013 to 2026). Any weakening or degeneration, especially through lack of use. "Progressive neuronal atrophy in AD is associated with downregulation in the levels of Brain-Derived Neurotrophic Factor (BDNF)/cAMP response element binding protein (CREB) signaling." (PMID 38339117, 2024). "Neuronal atrophy in the prefrontal and limbic regions was shown to be is associated with low levels of BDNF and other neurotrophic factors." (PMID 37954877, 2023). "A decrease in the levels of brain-derived neurotrophic factor (BDNF), a neurotrophic protein, is linked to neuronal atrophy, leading to depressive symptoms." (PMID 34440543, 2021). "Furthermore, lower levels of BDNF were associated with neuronal atrophy and reduced synaptic plasticity." (PMID 38549752, 2024). "Since the striatum does not produce BDNF but depends on it for its proper function, abnormalities in anterograde transport and reduced gene expression from brain regions supplying BDNF to the striatum might cause neuronal dysfunction and striatal atrophy." (PMID 25221473, 2014). "GDNF overexpression in 3xTg-AD mice has shown cognitive improvements with concomitant BDNF up-regulation, suggesting a synergistic neuroprotective effect against neuronal atrophy." (PMID 38067101, 2023). "These deficits in synaptic plasticity exhibited a progressive characteristic, with a reduction of BDNF levels that preceded synaptic atrophy during the stress procedure." (PMID 37989582, 2023). "The dysfunction and reduction of BDNF has been correlated with neuronal atrophy and synaptic damage." (PMID 34772918, 2021). "In depressive individuals, decreased level of BDNF leads to hippocampal atrophy and prefrontal cortex atrophy." (PMID 30524221, 2018). "Exposure to different types of physical or social stress can induce dendritic atrophy and reduce neurogenesis in the hippocampus of rodent models by down-regulating BDNF levels." (PMID 29097744, 2017). "If stress-related BDNF downregulation leads to neuronal atrophy and disorder, a stress-reducing intervention, in turn, could increase BDNF levels, thus promoting brain health and potentially even counteracting disorder development as a preventive intervention." (PMID 39896238, 2025). "Since BDNF is important for neurogenesis, hippocampal atrophy may be attributed to lower BDNF levels, as seen in depressed patients." (PMID 36499240, 2022). "Chronic stress leads to sustained decreases in neuroprotective factors (e.g., brain-derived neurotrophic factor (BDNF) expression and signaling) that damage plasticity, fostering neuronal atrophy and synaptic depression, particularly in the PFC and hippocampus." (PMID 36360672, 2022). "Under stressful environment, hippocampal atrophy and decreased BDNF secretion were found in mice." (PMID 30524221, 2018). "Of those HV-relevant SNPs identified from previous studies and AD-risk SNPs that were available in the genotyped sample (16/28 SNPs), none were significantly associated with HV atrophy, including the BDNF SNP, rs6265." (PMID 25625606, 2015). "In addition, abnormal excess of GCs may also induce neuronal atrophy and synaptic dysfunction (e.g., disturbance of integrity of synaptic skeleton) by upregulation of tau hyperphosphorylation and suppression of brain-derived neurotrophic factor (BDNF)." (PMID 35260821, 2022). "This could imply that smaller hippocampal volume, and not necessarily atrophy, is associated with BDNF levels." (PMID 31127089, 2019). "In non-atrophy group, the expression of serum brain-derived neurotrophic factor (BDNF) increase with resistance exercise training (RET), however a decrease was found in the atrophy group." (PMID 37349732, 2023).
glioblastoma (32 papers, 2014 to 2025). The most malignant astrocytic tumor (WHO grade IV). "The effect of miR-1 on BDNF expression was also examined in another recent study, which found that overexpressing miR-1 in U-87 MG cells (a human primary glioblastoma line) caused a 50 % decrease in BDNF protein levels." (PMID 25601223, 2015). "Conversely, glioblastomas with higher BDNF serum levels had a decreased immune cell signature, consistent with the lower immune cell signature of high-neural tissue samples." (PMID 38760585, 2024). "The binding of BDNF to its receptor TrkB on glioblastoma cells, for example, has been shown to promote tumor development and invasion by activating many signaling pathways such as PI3K/AKT, MEK/ERK, and PLC." (PMID 38523646, 2024). "Neurons, have been shown to alter glioblastoma cell behaviour through the synthesis of BDNF and neuregulin-1 (NRG1)." (PMID 38523646, 2024). "One study evaluated the association between BDNF and physical activity in HGG, finding that BDNF produced by glioblastoma-differentiated cells acts on glioblastoma stem cells, fostering their growth through paracrine signaling." (PMID 37959303, 2023). "Mir-489-3p can also inhibit cell proliferation by targeting the brain-derived neurotrophic factor-mediated PI3K/AKT pathway in glioblastoma cells and suppress proliferation by targeting JAG1 in bladder cancer cells." (PMID 36207684, 2022). "The model proved to be a valid prognostic immune-related biomarker for MM patients, BDNF is considered to be an effective protective factor to participate in the pathogenesis of glioblastoma." (PMID 35568859, 2022). "Towards that end, we made use of human retinal pigment epithelial (ARPE-19) cells and human glioblastoma cell-line U-87 MG that secrete a detectable amount of endogenous BDNF." (PMID 24804980, 2014). "Since BDNF has multiple functions in the central nervous system, we also tested pre-miRs in U-87 MG glioblastoma cells that originate from the CNS." (PMID 24804980, 2014). "Glioblastoma proliferation, invasion, and resistance to apoptosis are promoted by the binding of TrkB receptors on glioblastoma cells to molecules released from neurons such as brain-derived neurotrophic factor (BDNF) and neuroligin-3 (NLGN3)." (PMID 41208963, 2025). "In addition, there are numerous paracrine signaling besides brain-derived neurotrophic factor (BDNF) that can exert an influence on glioblastoma, so further studies are needed to reveal them in the future." (PMID 40999491, 2025). "Our findings suggest that BDNF could assist in stratifying patients with glioblastoma based on their neural subgroup, potentially facilitating targeted therapy in the future and that the neural signature is detectable in circulating extracellular vesicles." (PMID 38760585, 2024). "While the BDNF–TrkB axis may represent a therapeutic target for high-neural glioblastoma, we further identified low-neural tumors as immune-enriched based on transcriptomic and cell state composition analysis." (PMID 38760585, 2024). "Prior to using SIM-A9, we determined BDNF expression levels in U-87MG (human glioblastoma/astrocytoma cell line) to see if we could modulate BDNF expression in these cells using LNP-siBDNF formulations." (PMID 32287325, 2020). "Finally, BDNF appears to be crucial in the pathogenesis and development of brain tumors such as glioblastoma by reorganizing its microenvironment." (PMID 33096634, 2020). "An earlier study showed that immature dentate granule cells (DGCs) emit brain-derived neurotrophic factor (BDNF) and that glioblastoma stem cells (GSCs) express neurotrophic receptor kinase 2 (NTRK2), also known as TrkB, an appropriate receptor for BDNF." (PMID 36865549, 2023). "To functionally investigate the impact of KDM5C overexpression on the BDNF and HIF1A levels, we transiently transfected the T98G glioblastoma cell line with KDM5C plasmid." (PMID 36142158, 2022).
glioblastoma (continued). "In our previous study, we had demonstrated a retardation of proliferation of glioblastoma cell cultures, Grade IV, after GQIcombi treatment: cytostatic G-quadruplex bi-(AID-1-T) oligonucleotide, SB431542 (SB), purmorphamine (PRM), LDN-193189 (LDN), and Brain-Derived Neurotrophic Factor (BDNF)." (PMID 38988707, 2024). "Finally, carnosine has also been shown to stimulate the secretion of neurotrophins such as Brain-Derived Neurotrophic Factor (BDNF) and Nerve Growth Factor (NGF) in human glioblastoma-derived U-87 MG cells, but not in neuronal SH-SY5Y cells, suggesting a cell type-specific mechanism of action." (PMID 41527663, 2025).